NKILA (NF-kappaB interacting lncRNA)
Gene: Long non-coding RNA gene on chromosome 20 (57,710,156 to 57,712,780, forward strand). Ensembl gene ENSG00000278709.
Diseases named in the same sentence as NKILA in open-access papers:
NKILA is named in the same sentence as 58 diseases in open-access papers, as found by Europe PMC text mining. Sharing a sentence is not in itself a finding about the gene and the disease. The quoted sentences say what the papers report.
breast carcinoma (63 papers, 2015 to 2025). "LncRNA NKILA has similarly been associated with reduced breast cancer metastasis despite its correlation with poor patient outcomes." (PMID 39997609, 2025). "While decreased NKILA expression levels in breast tumors are associated with metastasis and poor prognosis of breast cancer patients, NKILA has been more recently shown to be also critical for immune evasion of breast and lung cancer cells." (PMID 37782337, 2024). "Assessments of lncRNAs profiles association with clinicopathological features of breast cancer patients showed that the expression level of NKILA, and NBAT1 lncRNAs were related to the tumor size." (PMID 36274054, 2023). "Downregulated expression of NKILA is associated with metastasis and invasiveness in breast cancer patients." (PMID 36770654, 2023). "A gene at chromosome 20q13 encoded NKILA, which first exerted the antimetastatic abilities of breast cancer cells." (PMID 31214490, 2019). "While NKILA is abundantly expressed in the normal breast epithelia, its low expression associates with breast cancer metastasis and poor patient prognosis." (PMID 31784542, 2019). "Previous reports have thoroughly studied molecular mechanisms underlying dysregulated NKILA expression in breast cancer." (PMID 29348395, 2018). "NKILA is a lncRNA encoded by a gene on chromosome 20q13 and was initially identified as an NF-κB-induced lncRNA in breast cancer." (PMID 29379981, 2018). "Encoded by a gene at chromosome 20q13, NKILA was first shown to exhibit an inhibitory effect on the metastatic abilities of breast cancer cells." (PMID 29368602, 2018). "Our previous report suggested the reduced NKILA is associated with clinical invasion and metastasis of breast cancer." (PMID 27613832, 2016). "Lower levels of NKILA expression are associated with poorer outcomes in breast cancer patients." (PMID 39553554, 2024). "Besides, lncRNA NKILA was shown to suppress breast cancer metastasis and was associated with poor patient prognosis." (PMID 32929060, 2020). "In addition, reduced NKILA expression is associated with breast cancer metastasis and poor patient prognosis." (PMID 32194993, 2020). "NKILA, initially reported in the context of breast cancer, functions as a tumor suppressor by inhibiting NF-κB-mediated metastasis." (PMID 39553554, 2024). "NKILA has been initially identified as a cytoplasmic lncRNA that is induced by inflammatory cytokines via the NF-κB pathway in human breast cancer cells." (PMID 37782337, 2024). "Conversely, silencing NKILA in the context of an adoptive cell therapy in a patient-derived xenograft model of breast cancer can reduce AICD in T lymphocytes and improve therapy efficacy by preventing tumor immune evasion." (PMID 37782337, 2024). "Overexpression of NKILA in tumor-specific CTL and TH1 cells was associated with their apoptosis and shorter patient survival in breast cancer." (PMID 36810034, 2023). "LncRNA-NKILA plays a role in preventing tumor growth and inhibiting metastasis in melanoma, breast cancer and other types of solid tumors, while the expression of NKILA is enhanced by the nuclear factor NF-κB." (PMID 36601121, 2022). "Overexpression of NKILA resulted in the inhibition of metastasis and the increase in apoptosis by repression of NF-κB signaling activity in breast cancer cells, indicating the tumor suppressor property of NKILA." (PMID 35052468, 2022). "NKILA has been reported to suppress NF-κB signaling pathways by blocking IkBα phosphorylation in breast cancer, non-small cell lung cancer and nasopharyngeal carcinoma." (PMID 35052468, 2022). "For instance, NKILA was proved to interact with the NF-κB complex in the cytosol to regulate the progression of breast cancer cells." (PMID 34990401, 2022). "LncRNA, NKILA (NF-KappaB Interacting LncRNA), localized to 20q13.31, was firstly found to be downregulated in breast cancer." (PMID 35052468, 2022).
breast carcinoma (continued). "NKILA was recently found to be up-regulated by pro-inflammatory cytokines in breast cancer, and there is increasing evidence that NKILA can act as an inhibitor of NF-κB in cellular inflammation and regulate the body’s inflammatory response." (PMID 35730575, 2022). "NKILA was shown to suppress TGF-beta-induced epithelial-mesenchymal transition by blocking NF-kappaB signalling in breast cancer." (PMID 34391383, 2021). "According to previous studies, lncRNA NKILA has been reported to be a tumor suppressor, which has been negatively correlated with metastasis and prognosis in breast cancer." (PMID 34885054, 2021). "For example, in lung and breast cancer, lncRNA NKILA can upregulate the sensitivity of tumor-specific cytotoxic T lymphocytes and type 1 helper T cells to activation-induced cell death by inhibiting NF-κB activity, thereby facilitating immune escape." (PMID 34925511, 2021). "LncRNA NKILA was first found up-regulated by the inflammatory cytokine TNF-α through the NF-κB pathway in breast cancer." (PMID 34123857, 2021). "For example, lncRNA NKILA suppresses breast cancer metastasis by interaction with p65 and blocking IκB phosphorylation." (PMID 34370213, 2021). "For instance, decreased expression of NF-κB interacting lncRNA (NKILA) is correlated with breast cancer metastasis through regulation of NF-κB signaling in breast cancer patient." (PMID 32305959, 2020). "For instance, lncRNA NKILA suppresses transforming growth factor β (TGF-β)-induced EMT by blocking nuclear factor κB (NF-κB) signaling in breast cancer." (PMID 31927328, 2020). "LncRNA NKILA has been reported to directly bind to NF-κB, acting as a modulator to block the activation of the NF-κB pathway and suppress breast cancer metastasis." (PMID 32461377, 2020). "In the previous reports, a series of lncRNAs (such as CTBP1-AS in PCa, lncARSR in renal cancer, and NKILA in breast cancer were reported to play key roles in regulating cancer progression." (PMID 33082888, 2020). "LncRNA NKILA was first found upregulated by inflammatory cytokines TNF-α through NF-κB pathway in breast cancer." (PMID 32929060, 2020). "NKILA was first identified as an lncRNA upregulated by inflammatory cytokines via NF-κB Signaling in breast cancer." (PMID 32015685, 2020). "Mechanistically, NKILA binds to NF-κB/IκB complex and inhibits NF-κB signaling through masking the phosphorylation sites of IκB and stabilizing the complex, leading to breast cancer metastasis." (PMID 32929060, 2020). "Originally identified in breast cancer and located in the cytoplasm, NKILA masks the phosphorylation motifs of IκB by interacting with p65-IκB subunits thereby suppressing NF-κB activation." (PMID 31784542, 2019). "In conclusion, it has been shown that lncRNA NKILA can modulate the TGF-β-induced EMT of breast cancer." (PMID 31214490, 2019). "As inhibition of EZH2/1 and EZH2‐only elicited diametric effects on NKILA expression in the two breast cancer cell lines, we explored the potential contribution of EZH1 to these cell‐specific events." (PMID 31282094, 2019). "We define a novel signaling loop encompassing canonical and non‐canonical actions of EZH2 on the regulation of NF‐κB/NKILA homeostasis, with relevance to breast cancer treatment." (PMID 31282094, 2019). "Our evaluation of homeostatic levels of EZH2, NF‐κB and NKILA corresponds to expression levels established in previous studies of breast cancer cell lines and patient‐derived tumours." (PMID 31282094, 2019). "Consistent with the important regulatory role of NKILA in breast cancer, we demonstrate that NKILA regulates the progression of NPC cells by regulating NF-κB pathway activity." (PMID 31430288, 2019). "Here, we investigated the interaction between EZH2 and the NF‐κB/NKILA signaling axis in a non‐tumourigenic breast epithelial cell line and in two breast cancer cell lines displaying differential hormone receptor expression." (PMID 31282094, 2019).
breast carcinoma (continued). "It has been reported that lncRNA NKILA activates NF-κB signaling in MDA-MB-231 breast cancer cells by stimulating up-regulation, such as TNF-α or lipopolysaccharide (LPS)." (PMID 31383786, 2019). "NKILA is an NF-κB-interacting lncRNA, our previously study found it can be upregulated by inflammatory cytokines in breast cancer." (PMID 31430288, 2019). "NKILA is firstly identified as upregulated by inflammatory cytokines through NF-κB pathway in breast cancer, in return NKILA regulate the metastasis of breast cancer via NF-κB pathway." (PMID 31430288, 2019). "In theory, the mechanism of NKILA in downregulating the TSCC metastatic capacity is identical as to that in breast cancer." (PMID 29368602, 2018). "The long non-coding RNA (lncRNA) NKILA (nuclear transcription factor NF-κB interacting lncRNA) functions as a suppressor in human breast cancer and tongue cancer." (PMID 29348395, 2018). "In the previous study of breast cancer, NKILA transcription was induced by NF-κB signaling pathway, while NKILA expression and NF-κB activity were negatively correlated." (PMID 29416703, 2018). "NKILA has been reported to interact with and influence the activation of NF-κB signaling in breast cancer." (PMID 29379981, 2018). "In light of the remarkable relationship between NF-κB and the invasiveness of tumor cells, Liu and colleagues attempted and successfully confirmed the putatively negative regulation of breast cancer metastasis by NKILA." (PMID 29368602, 2018). "Nuclear factor-κB interacting lncRNA (NKILA) is major inhibiting checkpoint for NF-κB activation in breast cancer." (PMID 29368602, 2018). "Previous study found NKILA can suppress the migration and invasion of breast cancer and tongue squamous cell carcinoma cells via directly binding with NF-κB: IκB complex, thereby inhibiting IKK-induced IκB phosphorylation and NF-κB activation." (PMID 28412955, 2017). "The previous studies found that NKILA interacted with and suppressed the nuclear translocation of NF-KappaB, which influenced metastasis and prognosis in breast cancer." (PMID 28412955, 2017). "NKILA inhibits breast cancer metastasis, specifically through binding and masking the IKB phosphorylation motif, and thus, preventing the activation of the NF-kB pathway." (PMID 28558830, 2017). "Cytoplasmic lncRNA NKILA suppresses breast cancer metastasis via the mechanism where NKILA directly interacts with NF-κB/IκB and inactivates NF-κB inflammatory signaling." (PMID 28978149, 2017). "Previous study found that the expression of NKILA was regulated by TNF-α or IL1β induced NF-κB activation in breast cancer cells." (PMID 28412955, 2017). "It was reported that NKILA interacted with and influenced the activation of NF-κB in breast cancers." (PMID 28412955, 2017). "This expression pattern of NKILA in TSCC was consistent with our previous observation in breast cancer that NKILA expression in normal breast tissues was significantly higher than that in the ductal carcinomas in-situ without metastasis or metastasis." (PMID 27613832, 2016). "Moreover, the long-chain non-coding RNA NKILA has been found to regulate the expression of Hsp90α, NF-κB, and β-catenin in breast cancer cells." (PMID 38727789, 2024). "Consequently, NKILA inhibits breast cancer metastasis and patients with low NKILA expression show poor survival with metastasis tendency." (PMID 38933287, 2023). "Fourthly, NKILA was first shown to suppress NF-κB signaling in breast cancer." (PMID 35052468, 2022). "In addition, NKILA has also been shown to inhibit tumor invasion and migration in epithelial cancers, such as breast cancer, hepatocellular carcinoma and tongue squamous cell carcinoma." (PMID 35052468, 2022). "NKILA is another lncRNA upregulated by TLR-4 stimulation in MDA-MB-231 in breast cancer cells." (PMID 35895506, 2022).
breast carcinoma (continued). "Herein, in NHL cells, the downregulation of NKILA resulted in an increase in cellular proliferation and decrease in cell death, consistent with the tumor suppressor role of NKILA in multiple tumors, including melanoma, lung cancer, rectal cancer, laryngeal cancer and breast cancer." (PMID 35052468, 2022). "NKILA could directly bind to the NF-κB/IκB complex and inhibit NF-κB signaling from suppressing breast cancer metastasis." (PMID 34123857, 2021). "For example, in breast cancer, the lncRNA NKILA induced by the NF-κB signaling pathway can bind to the NF-kb/IkB complex and mask the phosphorylation site of IkB, which inhibits IKK-induced phosphorylation of IkB and activation of NF-κB, thereby inhibiting the metastasis of breast cancer cells." (PMID 34123804, 2021). "NKILA acts as a NF-κB regulator to inhibit breast cancer metastasis 56-58." (PMID 32194786, 2020). "In details, NKILA could directly bind to NF-κB/IκB complex and inhibit NF-κB signaling to suppress breast cancer metastasis." (PMID 32929060, 2020). "Furthermore, NKILA suppresses breast cancer invasiveness, and NKILA expression was an independent predictor of breast cancer patients' prognosis." (PMID 32015685, 2020). "In addition, lncRNA NKILA suppressed breast cancer metastasis in a xenograft mouse model; and low NKILA was associated with poor patient prognosis." (PMID 32929060, 2020). "Among these dysregulated RNAs, NKILA was found significantly downregulated in NPC, the decline of NKILA was more pronounced in patients with distant metastases, consistent with previously reported in breast cancer, Hepatocellular carcinoma and laryngeal cancer." (PMID 31430288, 2019). "We investigated the influence of EZH2/1 restriction on cell motility and EMT to determine whether the EZH2/NF‐κB/NKILA signaling axis can be manipulated to enhance therapeutic intervention in breast cancer." (PMID 31282094, 2019). "NKILA can form a ternary complex with the NF-κB/IκBα complex by direct binding to the P65 subunit, thereby affecting the phosphorylation of the NF-κB-related pathway and its mediating breast cancer metastasis." (PMID 29941860, 2018). "NF-KappaB Interacting LncRNA (NKILA), encoded by a gene at chromosome 20q13 just near by the prostate transmembrane protein androgen induced 1 (PMEPA1) (also named solid tumor associated gene 1, STAG1), is upregulated by NF-κB in breast cancer." (PMID 28412955, 2017). "Interestingly, in high metastatic breast cancer cells, overexpression of microRNA-103/107 targeted and degraded NF-κB-interacting LncRNA, NKILA, which can interact with NF-κB/IκB to prevent overactivation of NF-κB pathway." (PMID 27409165, 2016). "However, many recent studies have examined the roles of various lncRNAs in cancer; examples include MALAT1 in small cell lung carcinoma, lncRNA-ATB in hepatocellular carcinoma, and NKILA in breast cancer." (PMID 27223436, 2016). "Our previous study in breast cancer showed IKK kinase inhibitor could abolish the effects of NKILA-shRNA on IκB phosphorylation and NF-κB activation, indicating IKK is the upstream signal protein of NKILA." (PMID 27613832, 2016). "For example, lncRNAs such as HOTAIR (breast cancer), NKILA (breast cancer metastasis), NBAT1 (neuroblastoma), MALAT1 (lung, breast, prostate and cervix cancer), MDC1-AS (bladder cancer), lncRNA-886 (esophageal and gastric cancers) and PCAT-1 (prostate cancer) have been implicated in tumorigenesis." (PMID 26087192, 2015). "In addition, in breast cancer cells, some oncogenic microRNAs, such as miR-103 or miR-107, could directly target and downregulate the expression of NKILA, which was confirmed by the luciferase reporter assay." (PMID 35052468, 2022). "Recently, a long non-coding RNA (lncRNA) NKILA (nuclear transcription factor NF-κB interacting lncRNA) which could mask the phosphorylation site of IκB, inactivate the NF-κB signaling and suppress breast cancer metastasis has attracted our attention." (PMID 29348395, 2018).
breast carcinoma (continued). "Research has identified several lincRNAs, such as MALAT1, NKILA, and ANCR, that inhibit breast cancer metastasis, in contrast to lincRNAs known to promote it." (PMID 39997609, 2025). "In breast cancer, LINC01615, the long non-coding NKILA and MALINC1 have been reported to regulate breast cancer progression and metastasis." (PMID 36672487, 2023). "NKILA is a lncRNA that interacts with NF-κB and modulates T cell sensitivity to AICD by inhibiting NF-κB activity in lung caner and breast cancer microenvironment." (PMID 36810034, 2023). "The healthy breast epithelia abundantly express the LncRNA NKILA and long GAS5, but their low expression correlates with metastasis of breast cancer." (PMID 36770654, 2023). "NKILA-depleted CTLs show attenuated AICD and thus inhibit the in vivo propagation of breast cancer and non-small cell lung cancer." (PMID 38933287, 2023). "The results revealed that some circulating lncRNAs (MEG3, NBAT1, NKILA, GAS5, EPB41L4A‐AS2, Z38, and BC040587) were significantly down‐regulated in breast cancer patients compared to healthy women." (PMID 36274054, 2023). "As an example, Liu and colleagues identified a lncRNA NKILA which showed dramatic upregulation upon TNF-α treatment in breast cancer cells and suppressed breast cancer metastasis." (PMID 35842651, 2022). "In another report, NKILA was shown to be up-regulated by TGF-β to block NF-κB signaling, thereby suppressing the TGF-β-induced tumor metastasis in breast cancer." (PMID 34123857, 2021). "Meanwhile, studies revealed that in contrast to those metastasis-promoting lncRNAs, other lncRNAs, such as MALAT1, NKILA, and ANCR can suppress breast cancer metastasis." (PMID 32929060, 2020). "Partial silencing of NKILA significantly increased NF‐κB, EZH2 and H3K27 methylation in both breast cancer cell lines." (PMID 31282094, 2019). "Here, we demonstrate that overexpression of NKILA promotes apoptosis and represses the invasion of NPC cell lines as reported in breast cancer cells." (PMID 31430288, 2019). "NKILA was reported to be upregulated by more than 12-fold by TNF-α- and IL-1β-induced NF-κB activation in breast cancer." (PMID 29379981, 2018). "LncRNA NKILA inhibited IKK-induced IκB phosphorylation and NF-κB activation by forming a stable complex with NF-κB/IκB, thus preventing over-activation of NF-κB pathway to suppress breast cancer metastasis." (PMID 32929606, 2020). "As expected, partial NKILA silencing exerted a negative effect in both breast cancer cell lines by augmenting nuclear NF‐κB levels, EZH2 expression and H3K27 methylation." (PMID 31282094, 2019). "In contrast, non‐specific inhibition of EZH2/1 in ER+ breast cancer cells may induce a more robust response over tazemetostat delivery alone, as EZH1 may negatively regulate NKILA under EZH2 inhibition." (PMID 31282094, 2019). "Partial NKILA silencing showed no major effect on EMT markers in either breast cancer cell line, however, miR‐103 delivery in HMECs dramatically attenuated the expression of Vimentin and E‐cadherin, while increasing N‐cadherin expression levels." (PMID 31282094, 2019). "We found that the expression of NKILA was mainly regulated by classical TGF-β signal pathway in NSCLC cells rather than NF-κB pathway reported in breast cancer." (PMID 28412955, 2017). "The lncRNA NKILA lacking CAR-N cannot inhibit breast cancer cell migration." (PMID 40221424, 2025). "Meanwhile, down‐regulation of lncRNAs such as NF‐κB interacting lncRNA (NKILA), EPB41L4A antisense RNA 2 (EPB41L4A‐AS2), and Growth arrest‐specific transcript 5 (GAS5) inhibit breast cancer progression and may advance invasion and metastasis of breast cancer." (PMID 36274054, 2023). "Upregulated lncRNA NKILA expression via NF-κB signaling participates in the negative feedback loop of NF-kB regulation, and thus, contributes to the metastasis and poor prognosis of breast cancer." (PMID 35264742, 2022).